CSF1R (colony stimulating factor 1 receptor)
Diseases named in the same sentence as CSF1R in open-access papers (continued):
Sharing a sentence is not in itself a finding about the gene and the disease.
tumor (continued). "However, current clinical studies have so far not shown that CSF-1R inhibitors, as a monotherapy, delay tumor growth." (PMID 34683963, 2021). "Additionally, we have recently shown that CSF-1R inhibition leads to a significant reduction in TAMs and when combined with PARP inhibitor therapy results in an increase in overall survival, with some mice experiencing tumor-free survival for at least 1 year." (PMID 33968034, 2021). "However, in non–tumor-bearing mice, anti-CSF1R treatment did not significantly reduce necrotic lesions produced by chemoimmunotherapy." (PMID 34101617, 2021). "In addition, combination of CSF-1R and CXCR2 inhibitors resulted in strong anti-tumor effect." (PMID 35127700, 2021). "Combination of CSF1R and CXCR2 inhibitor can effectively reduce the number of TAMs and inhibits polymorphonuclear myeloid suppressor cells (PMN-MDSC) in TME, which could delay tumor growth." (PMID 33391402, 2021). "In fact, the median survival of CD8 high patients tended to be shorter than CD8 low patients among those with CSF1R high tumors, implying that in the presence of CSF1R macrophages, CD8 infiltration might be disadvantageous for the patient because they are rather suppressed, favoring tumor evasion." (PMID 34067348, 2021). "The blockade of CSF1R signaling could be a promising anti-cancer therapy, presumably by depleting the TME of immunosuppressive macrophages and releasing anti-tumor immune responses However, most of the drug development is still in the early stage, with limited success in clinical cancer trials." (PMID 34830850, 2021). "In addition to CSF1/CSF1R blockade, macrophage reprogramming using HDAC inhibitors or agonistic anti-CD40 antibodies increases the expression of PD-L1 on macrophages, which limits the anti-tumor effect of reprogrammed TAMs." (PMID 34248982, 2021). "CSF-1 recruits MDSCs with the ability to support tumor immune escape by binding to CSF-1R expressed by MDSCs, and studies demonstrated that selective inhibitors PLX3397 and GW2580 could block their signaling by targeting CSF-1R." (PMID 34527668, 2021). "For example, in ongoing clinical trials targeting CSF-1, anti-CSF-1R monoclonal antibodies (such as IMC-CS4 in NCT01346358) block the binding of CSF-1 and IL-34 to CSF-1R and abrogate the recruitment and survival of TAMs, leading to TAM apoptosis and inhibition of tumor growth." (PMID 34683963, 2021). "In addition, lack of NR4A1 results in reduced levels of colony-stimulating factor-1 receptor (CSF-1R) expression, which decreases the migratory capacity of inflammatory cells and subsequently hinders cell chemotaxis and tumor infiltration." (PMID 33634114, 2021). "However, in clinical practice, a lack of evidence on tumor control has limited the use of the combination of CSF1/CSF1R blockade and PD-L1/PD-1 monoclonal antibody to treat solid tumors." (PMID 34248982, 2021). "These drugs, suppressing tumor progression and/or metastasis, either block monocyte infiltration (e.g., inhibition of CCL2/CCR2 chemokine axis), repolarize TAMs (e.g., the blocking of CD47 or MARCO or stimulating CD40 or TLRs) or deplete TAMs (e.g., CSF-1R blockade or bisphosphonate toxicity)." (PMID 32752088, 2020). "For instance, dual inhibition of PI3K-γ and CSF-1R by a nanomicelle encapsulating the PI3K-γ inhibitor BEZ 235 and CSF-1R-siRNA has been reported to largely diminish M2 macrophage infiltration and remove the immune blockade in the tumor microenvironment of PDAC." (PMID 33505964, 2020). "Interestingly, a combination of anti-CD40 agonist and inhibition of CSF-1R induced macrophage pro-inflammatory phenotype prior CSF-1R mediated elimination, which was sufficient to reinvigorate CD8+ T cell response in transplanted tumours that were either resistant or sensitive to ICBs." (PMID 31331034, 2019). "Interestingly, another RTK found to be highly activated in our samples (5/7 tumor samples) was macrophage colony-stimulating-factor-1-receptor MCSFR (CSF1R) (data not shown)." (PMID 30863365, 2019).
tumor (continued). "Interestingly, some investigations using CSF-1R or CCR2 inhibitors showed that the anti-tumor efficacy of these drugs was to reprogram TAMs, rather than macrophage depletion, as supposed previously." (PMID 31878087, 2019). "Similarly, anti-CSF-1R (colony-stimulating factor 1 receptor) treatment with Pexidartinib (PLX3397) specifically decreased M2 tumor-promoting macrophages, without benefitting GBM patients." (PMID 31708781, 2019). "In mouse models of cancer, CSF1R blockades synergize with the agonistic CD40 antibodies to remove inhibitory immune populations and to drive endogenous antitumor immune responses, resulting in improved tumor clearance and significantly lengthened overall survival." (PMID 31805946, 2019). "In addition, it has been recently shown that CSF1R is expressed in NLCs and in lymph nodes derived from CLL patients, and that neutralization or inhibition of CSF1R inhibits NLC formation, decreases CLL cell viability, and enhances the anti-tumor effects of ibrutinib." (PMID 29872489, 2018). "Yet, single-agent use targeting CSF1R did not yield clinical benefits in various tumor types." (PMID 30158932, 2018). "CSF1R expression was also absent in PDAC tumor cell lines derived from mouse and human." (PMID 29719257, 2018). "These macrophages may be more resistant due to reduced CSF‐1R expression, or reflect a population that has not yet been polarised by the tumour microenvironment." (PMID 30442705, 2018). "Given the dramatic effect of CSF1R inhibition as a single agent compared to our previous work on CXCR2 inhibition where efficacy in late-stage tumors was only observed in combination with anti-checkpoint inhibition, we wanted to compare the effect of these inhibitors on tumor gene expression." (PMID 29719257, 2018). "Importantly, inhibition of CSF1R signaling can reprogram immunosuppressive TAM responses and generate anti-tumor responses in multiple mouse tumor models, and a similar approach in the RENCA model may yield similar results." (PMID 30388137, 2018). "Recent studies have shown that signaling pathways regulated by TLRs, CSF1R, PI3Kγ, and BTK control macrophage polarization; here, we showed that CD11b promotes miRNA Let7a expression and inhibits Myc expression to control of macrophage polarization and tumor immune responses (Schematic)." (PMID 30568188, 2018). "However, up to now, the use of pharmacological agents able to decrease TAM infiltration in the tumor stroma such as the colony stimulating factor 1 receptor inhibitor PLX3397 have not shown the expected results." (PMID 29262593, 2017). "Furthermore, treatment with neutralising anti-CSF-1R or anti-CSF1 antibodies can lead to a compensatory increase in granulocyte colony stimulating factor (CSF3), which stimulates an increase in neutrophils at the primary tumour site and in metastatic deposits." (PMID 28210073, 2017). "Since MAMPCs continuously produce MAMs, a single treatment with CSF1R antagonist might not be sufficient in time or degree of inhibition to prevent metastatic tumor outgrowth." (PMID 29387063, 2017). "The results showing the presence of a hyperphosphorylated CSF1R protein in cHL cases highlight the importance of CSF1/CSF1R signalling in the recruitment of TAMs, and the importance of this pathway in the reciprocal crosstalk between tumour HRS cells and the microenvironment." (PMID 26066800, 2015). "However, expression of CSF-1R by tumor cells also indicates a non-macrophage functional role for the receptor." (PMID 25295160, 2014). "For example, sunitinib inhibits a number of growth factor receptors regulating both tumor cell proliferation/survival and tumor angiogenesis including vascular endothelial growth factor receptors, platelet-derived growth factor receptors α and β, c-Kit, FLT3, CSF1R, and RET." (PMID 24701565, 2014).
tumor (continued). "Particularly, cells expressing colony-stimulating factor-1 receptor (CSF1R), a crucial molecule for the differentiation of the macrophages, DCs, and other myeloid-derived monocytes, were almost completely eliminated by RAPA (second panel) in these tumor infiltrating myeloid cells." (PMID 24023896, 2013). "Moreover, the expression levels of CD86 (M1 macrophage marker) and CSF1R (M2 macrophage marker) were positively correlated with those of BECN1 (autophagy regulator) and BCL2 (only CD86) that were in turn correlated with MTOR expression in tumor B cells and in the CD86+ macrophage subtype." (PMID 41415285, 2025). "To determine whether blockade of CSF-1R signaling and subsequent inhibition of TMEM doorway opening prevented tumor cells from entering the vasculature, we collected the blood from the mice during sacrifice and measured the number of circulating tumor cells (CTCs)." (PMID 40646332, 2025). "Thus, the combination of IL-33 and anti-CSF1R or p38 inhibitor could avoid the negative immune regulation of IL-33-induced M2 polarization, which has synergistic anti-tumor effect." (PMID 38238529, 2024). "However, the pivotal role of the CSF-1R in facilitating BMBP transdifferentiation into B-MFs highlights its potential as a target for therapeutic intervention aimed at disrupting the generation of immunosuppressive TAMs and enhancing anti-tumor immune responses." (PMID 39457693, 2024). "Similarly, a phase 2 clinical trial (NCT02406781) showed that PD-1 inhibition alone was not sufficient to control tumour growth and that a combination of inhibition of the colony stimulating factor 1 receptor and the IDO pathway resulted in more effective tumour control." (PMID 39070147, 2024). "Notably, not all tumor cells expressed the receptor, but only a subset of cells with aggressive behavior, thereby indicating that CSF-1R could contribute to promoting tumor aggressiveness." (PMID 38254773, 2024). "Therefore, as CSF1 and FGF signals are both involved in the accumulation of tumor- promoting M2 macrophages, MDSCs, and Tregs, the dual inhibition of CSF1R and FGFR1 by sulfatinib may be more effective for cancer therapy than selective CSF1R inhibition." (PMID 37361567, 2023). "However, since macrophage proliferation in response to tumor supernatant might be not completely dependent on CSF-1R signaling, others tumor-released factors could be involved in TAMs self-renewal and activate specific metabolic signatures." (PMID 36359228, 2022). "We hypothesized that a GAMM depletion–repopulation approach would be beneficial, resulting in reduced tumor size and decreased neuroinflammation, and that 18F-DPA-714 is a suitable imaging readout for in vivo investigation of GAMM dynamics during the course of CSF-1R inhibitor therapy." (PMID 35115369, 2022). "However, there were no changes to CSF-1R expression during tumor growth in elderly mice (and compared to healthy) suggesting splenic macrophages from tumor-bearing mice could be refractory to CSF-1R signaling." (PMID 35821822, 2022). "However, insight into the whole-body distribution and tumor uptake of CSF1R mAbs is lacking." (PMID 34976826, 2021). "Similarly, the proportion of CD38+ TAMs was not altered after the addition of anti-CSF-1R in both tumor types in comparison with the original IT, and the number of Egr2+ TAMs only marginally decreased after the addition of anti-CSF-1R into treated mice with TC-1/A9 tumors." (PMID 34205330, 2021). "Similarly, alternative activation of CSF1R by IL34 did not affect tumor cell viability." (PMID 34067348, 2021). "However, following treatment, tumor cells had increased expression of PD‐L1 and effector T cells had increased expression of CTLA4, suggesting immune checkpoint blockade in conjunction with CSF1R blockade may have a synergistic effect." (PMID 30003190, 2018).
tumor (continued). "Of interest was the presence of the two CSF1R proteins of 100 and 150 kDa recognized by antibody FER216 in both WB and double IP experiments in cHL cases, that could be related to higher levels of receptor activation in the tumour microenvironment than in that of RLT." (PMID 26066800, 2015). "CSF1 upregulation stimulates the proliferation of neoplastic cells within the tumor and the recruitment of non-neoplastic macrophages that express the CSF1 receptor (CSF1R) to the synovium." (PMID 40392406, 2025). "Among the tumor cell lines tested, MCA205, MC38, and EMT6 lacked expression of FLT3, c-KIT, and CSF1R." (PMID 39782686, 2025). "Tumor-infiltrating lymphocyte (TIL) cultured from IDH-wildtype tumors demonstrated limited expansion following anti-PD-1, a CSF1R inhibitor, or a STAT3 inhibitor treatment, without clear cluster-specific differences." (PMID 40643554, 2025). "We demonstrate here that the combinations of EGFRxEGFR T-BsAb treatment with granulocyte and myeloid-depleting therapies (anti-Gr-1 and anti-CSF-1R) drove T cell infiltration into PDAC tumors and improved anti-tumor efficacy without side effects." (PMID 38650005, 2024). "We observed a similar result by flow cytometry, with anti-PD-L1 + anti-TIGIT treatment, but not anti-PD-L1 + anti-TIGIT + anti-CSF-1R treatment, driving a reduced expression of TOX in tumour CD8+ T cells." (PMID 38418879, 2024). "Besides these applications, PET imaging of CSF-1R could also be useful for the evaluation of new specific and sensitive CSF-1R inhibitors that have been emerged as potential TAM-therapies, as well as a better understanding of CSF-1R mechanisms involved in the tumor progression." (PMID 35526184, 2022). "Although CSF-1R inhibitor PLX3397 exerts anti-cancer effects by inhibiting recruitment of TAMs, yet it was argued that PLX3397 retards tumor growth by altering TAMs polarization rather than exhausting TAMs." (PMID 35672862, 2022). "Based on these findings, we proposed that LAPTM5, CSF1R, SLCO2B1 and C1QC are mainly expressed in immune cells rather than LUSC cells in tumor samples." (PMID 33428598, 2021). "Glufosinate did not affect tumor volume (Fig EV3A) and weight (Fig EV3B) either with or without anti‐CSF1R." (PMID 32885605, 2020). "In this regard, blockade of the CSF-1R with the chemical BLZ945 has been shown to improve survival and reduce tumor development in GBM bearing mice without any visible deleterious side-effects." (PMID 33178210, 2020). "Flow cytometry of tumor-infiltrated CD3+ T-cells revealed that only a subset of ~10% expressed Pdpn and that this is not changed in Csf1r-Cre; Pdpnflox/flox conditional knockout (cKO) mice." (PMID 30972297, 2019). "The treatment with RG7155 induced a selective apoptosis of CSF1R+CD163+ M2-like macrophages, but not of CD80+ M1-like macrophages, in vitro, and depleted TAMs in tumor-bearing mice." (PMID 29973487, 2018). "Overcoming TAM-mediated resistance involves strategies targeting their recruitment (e.g., CCL2/CCR2 blockade), survival/differentiation (e.g., CSF-1/CSF-1R inhibition), function (e.g., blocking “do not eat me” signals like CD47), or attempting to repolarize them towards an anti-tumor M1-like state." (PMID 40458806, 2025). "However, other reports indicated that inhibition of the CSF-1/CSF-1R axis did not obliterate all macrophages but pushed the TAMs toward the M1-like phenotype triggering CD8+ T cell activation and inhibiting tumor progression." (PMID 36902456, 2023). "Pleural and tumor levels of MPE-related proinflammatory mediators (IL-6; VEGF; monocyte chemoattractant protein-1, MCP-1; TNFA; secreted phosphoprotein 1, OPN; and macrophage inflammatory protein 2, MIP2) were not affected by macrophage CSF1R ablation." (PMID 35315360, 2022). "In addition, it was found that the use of olaparib and CSF-1R inhibitors in the BRCA-proficient mouse tumor model had no significant therapeutic effect, indicating that tumor immunotherapy was related to BRCA status." (PMID 36091750, 2022).
tumor (continued). "While the anti–CSF-1R antibody did not affect basal or MNK inhibitor–induced CD8+ T cell infiltration, the anti–CSF-1R antibody synergized with CGP57380 to control tumor growth." (PMID 35380995, 2022). "Notably, while TCGA data suggest abundant expression of CSF-1R in COAD tissues, substantially lower level of CSF-1R was identified in CRC lines, indicating that CSF-1R is not mainly expressed in tumor cells." (PMID 35444953, 2022). "Hence, we aimed for an improvement in the anti-tumor effect of combined IT by injecting either monoclonal antibodies to neutralize IL-10, TGF-β, and CSF-1R or the nor-NOHA inhibitor to block the activity of arginase." (PMID 34205330, 2021). "However, studies have shown that the utilization of CSF1R inhibitors to interfere the communication between TAM and tumor cells has not had any delay effect on tumor growth." (PMID 33224886, 2020). "Importantly, in combination with antibody-blocking CSF1R, lipofermata produced anti-tumor effects in the LLC model, suggesting a possible involvement of lipid uptake by TAMs, since anti-CSF1R alone did not produce beneficial effects." (PMID 32823961, 2020). "Depletion of macrophages and myeloid cells (anti-CSF1R) had little to no impact on the anti-tumor activity of hAB21, whereas depletion of neutrophils (anti-GR1) and CD8+ (anti-CD8) T cells abrogated anti-tumor activity indicating a requirement for both innate and adaptive immunity." (PMID 33256806, 2020). "However, a recent phase I study using a combination of a monoclonal anti-CSF-1R with paclitaxel in patients with advanced and metastatic solid tumors revealed TAM depletion but no clinically relevant anti-tumor activity." (PMID 31547627, 2019). "However, combined treatment with the two antibodies had no additive effect on MC38 tumor growth, suggesting that OLFML3 may act along the CSF1/CSF1-R axis." (PMID 34572851, 2021). "Furthermore, CSF-1R blockade significantly undermines the population of TAMs to a large degree, thereby reducing/diminishing M2-like TAM infiltration, but it has no definite effect on tumor cells." (PMID 33505964, 2020). "Furthermore, the molecular mechanism of CSF1/CSF1R in OSA remains unclear; the positive correlation with the expression of CSF1R and CD4/CD68 is not clear that it must play the positive effect on prognosis, and it may also be as a cancer promoting factor that involved in tumor immune escape." (PMID 32850346, 2020). "However, despite having shown an effect on tumour growth in mouse models, this approach failed to improve overall survival in patients, suggesting that putative TAM subpopulations may be resistant to CSF-1R inhibition." (PMID 31973030, 2020).